DYDC1 (DPY30 domain containing 1)
Description:
Functions as part of axonemal radial spoke complexes that play an important part in the motility of sperm and cilia (By similarity). Plays a crucial role during acrosome biogenesis.
Synonyms: DPY30D1; bA36D19.5
Tractability: No criterion of Open Targets' tractability assessment is met for any kind of drug.
Gene: Protein-coding gene on chromosome 10 (80,336,105 to 80,356,755, reverse strand). Ensembl gene ENSG00000170788.
Subcellular location: Cytoplasm, cytoskeleton, flagellum axoneme
Subcellular location (Human Protein Atlas): End piece; Mid piece; Principal piece
Gene Ontology:
Molecular function: protein binding
Biological process: cilium movement; flagellated sperm motility
Cellular component: 9+2 motile cilium; axoneme; cilium; radial spoke; sperm flagellum; Set1C/COMPASS complex
Genetic constraint (gnomAD): Loss-of-function variants: 17 observed, 24.05 expected, observed/expected ratio (o/e) 0.71, 90% interval 0.48 to 1.06. The upper end of that interval is the gene's LOEUF score, 1.06, which puts it in group 4 of 6, group 1 being the genes least tolerant of losing a copy. Missense variants: 172 observed, 181.42 expected, observed/expected ratio (o/e) 0.95, 90% interval 0.84 to 1.08. Synonymous variants: 61 observed, 59.31 expected, observed/expected ratio (o/e) 1.03, 90% interval 0.84 to 1.27.
Homologues: Orthologues: macaque DYDC1 (94% identical), chimpanzee DYDC1 (94% identical), rabbit DYDC1 (86% identical), dog DYDC1 (84% identical), pig DYDC1 (83% identical), guinea pig DYDC1 (78% identical), mouse Dydc1 (71% identical), rat Dydc1 (71% identical), tropical clawed frog dydc1 (38% identical), zebrafish dydc2 (27% identical). Paralogues in human: DYDC2 (29% identical).
Diseases named in the same sentence as DYDC1 in open-access papers:
DYDC1 is named in the same sentence as 4 diseases in open-access papers, as found by Europe PMC text mining. Sharing a sentence is not in itself a finding about the gene and the disease. The quoted sentences say what the papers report.
Alzheimer disease (1 paper, 2021). A progressive, neurodegenerative disease characterized by loss of function and death of nerve cells in several areas of the brain leading to loss of cognitive function such as memory and language. "Moreover, C20orf85 has been linked to lung cancer and DYDC1 seems to be involved in acrosome biogenesis, although IQCK has recently been highlighted in several studies regarding Alzheimer’s disease." (PMID 34573434, 2021).
male infertility (1 paper, 2021). The inability of the male to effect fertilization of an ovum after a specified period of unprotected intercourse. "By contrast, Dydc1 has been reported to regulate acrosome biogenesis during mice spermatogenesis and Fbxo47 was shown to be specifically expressed in meiotic prophase I and gene knockout leads to male infertility in mice." (PMID 34499650, 2021).
DYDC1 also shares sentences with these, for which no sentence is quoted: lung carcinoma (1 paper); metastatic tumors (1).